IGF1 (insulin like growth factor 1)
Diseases named in the same sentence as IGF1 in open-access papers (continued):
Sharing a sentence is not in itself a finding about the gene and the disease.
tumor (continued). "In PDAC, autocrine insulin-like growth factor-1 (IGF-1) and paracrine insulin stimulate the IGF-1 receptor (IGF1R) and insulin receptor (IR) to increase tumor growth and glycolysis." (PMID 40630951, 2025). "Collectively, these data identify CAFs as the principal source of IGF1 in the CCA microenvironment and demonstrate that CAF-derived IGF1 activates tumor-cell IGF1R to drive proliferation, migration, invasion, and tumor growth." (PMID 41275311, 2025). "In the total tumor area, there were also more T-cells positive for membrane CD4 in high serum IGF-1 cases compared with low IGF-1 cases." (PMID 41184420, 2025). "These therapies not only help stabilize skeletal structure but also indirectly hinder tumor survival by depriving cancer cells of growth factors released during bone resorption, including TGF-β and IGF-1." (PMID 40426987, 2025). "Its proposed mechanisms include enhanced insulin sensitivity, reduced circulating insulin and IGF-1 levels, and activation of the AMPK–mTOR signaling pathway, collectively suppressing oncogenic signaling and tumor proliferation." (PMID 41300987, 2025). "The nomogram, integrating IGF-1 with the CTP and tumour volume, exhibited robust predictive accuracy with an area under the curve (AUC) of 0.84 for 2-year survival." (PMID 39624154, 2025). "Co-culture of B cells and melanoma cells leads to reciprocal changes in both cells, whereby tumor cell secretion of FGF2 induces B cell increases in FGFR1/FGFR3 signaling and IGF1, IL-1α/β and PDGF-A/B expression." (PMID 40663561, 2025). "•A nomogram using IGF-1, CTP score, and tumor volume predicts 2-year survival in HCC patients post-SBRT." (PMID 39624154, 2025). "This showed that universal (PI16+) fibroblasts from tumours show evidence of activation and inflammatory changes (including expression of FAP, COL1A1, IGF1)." (PMID 39757146, 2025). "IGF‐1 also stimulates the RAS/RAF/MAPK and JAK/STAT pathways, preventing apoptosis and promoting tumor metastasis." (PMID 40387523, 2025). "these genes, Insulin Like Growth Factor 1 (IGF1) and Secreted Frizzled Related Protein 1 (SFRP1), were found to be down-regulated in tumor tissues, while the third gene, SDC1, also known as Syndecan 1, was found to be up-regulated in tumor tissues." (PMID 41209699, 2025). "The RT-qPCR analysis revealed significantly decreased expression of ESR1, APOA1, IGF1, PPARGC1A, SERPINE1 and PON1 in tumor tissues compared with adjacent normal tissues (P < 0.05)." (PMID 40317014, 2025). "For instance, elevated insulin levels can stimulate cell proliferation via the insulin-like growth factor-1 (IGF-1) axis while inducing epithelial-mesenchymal transition (EMT), thereby enhancing tumor invasiveness." (PMID 41164182, 2025). "PITX1 is considered a tumor suppressor gene, and is known to influence the expression of GH1, and is related to IGF-1." (PMID 40951278, 2025). "IGF-1, secreted by the liver and by CAFs, activates the RAS/MAPK and PI3K/AKT signaling pathways by binding to the IGF-1R, thereby promoting tumor cell invasion and metastasis." (PMID 41164182, 2025). "More recently, short-term starvation was shown to sensitize non-small cell lung cancer (NSCLC) to PD-1 blockade in vivo by suppressing serum IGF-1 and IGF-1R activity in tumor tissue." (PMID 41184420, 2025). "Meanwhile, upon activation, osteoclasts induce bone resorption, releasing TGF-β, insulin-like growth factor-1 (IGF-1), calcium ions, and other substances stored in the bone matrix, thereby providing proliferation signals for tumor cells." (PMID 41357241, 2025). "Hyperinsulinaemia can increase circulating levels of insulin-like growth factor 1 (IGF-1), which has mitogenic and anti-apoptotic properties, potentially facilitating tumour initiation and progression." (PMID 41427040, 2025). "Among these, IGF1 and HGF/Met signaling predominantly drive proliferation, migration, invasion, and angiogenesis across various tumor types." (PMID 40659611, 2025).
tumor (continued). "Metuzumab, a chimeric anti-CD147 monoclonal antibody with Fc glycoform modification, enhances ADCC and inhibits tumor cell migration and invasion by suppressing the PI3K/Akt signaling pathway and insulin-like growth factor 1 (IGF-1) expression." (PMID 41479915, 2025). "Quantitative comparisons demonstrated significant reductions in GH, IGF-1, and PRL levels following tumor resection." (PMID 41470032, 2025). "This process releases calcium ions, transforming growth factor-β (TGF-β), and insulin-like growth factor 1 (IGF1), all of which promote tumor homing, angiogenesis, tumor proliferation, and further release of PTHrP, thereby perpetuating a “vicious cycle”." (PMID 40149349, 2025). "Fasting reduces IGF-1 signaling, leading to decreased activation of the PI3K/AKT and RAS/RAF/ERK pathways, which are critical for tumor cell survival and growth." (PMID 39940361, 2025). "In ESCC, CellChat analysis revealed that IGF1 and IGF2, from iCAFs and myCAFs, respectively, were predominant ligands targeting tumor cells." (PMID 41228323, 2025). "Insulin and IGF‐1 also enhance angiogenesis via VEGF signaling, facilitating tumor vascularization and dissemination." (PMID 40195579, 2025). "These limitations underscore the potential advantage of targeting the upstream GH–GHR axis, which can simultaneously reduce circulating IGF1 levels, suppress IGF1R signaling in the TME, and attenuate tumor-promoting pathways." (PMID 41515995, 2025). "GHRH antagonists exert their antitumor activity by binding to GHRH-R and SV1, thereby disrupting the autocrine/paracrine mitogenic signaling mediated by tumor-derived GHRH, IGF1, and IGF2." (PMID 40244089, 2025). "Insulin and insulin-like growth factor 1 (IGF-1) are potent promoters of cell proliferation and tumor cell survival." (PMID 41178954, 2025). "The silencing of IGF1R or treatment with antibodies binding IGF1 and IGF2, BI836845 or xentuzumab inhibited the growth of in vivo cocultured CAFs-tumor cell xenografts." (PMID 38892104, 2024). "IGF-1 and IGF-2 are known to enhance BC cell proliferation in vitro, and mouse models show that IGF-1R signaling promotes tumor growth in distant tissues." (PMID 39273251, 2024). "This suggests the development of a possible vicious cycle involving GH/IGF-1/GIP and their receptors in the liver, duodenum, and somatotroph tumor cells in the early stages of the disease." (PMID 37344722, 2024). "Firstly, aberrant processing of pro‐IGF‐2 in certain tumours leads to increased levels of ‘big’ IGF‐2, which have less efficacy to bind to IGF receptors, thereby potentially lowering the calculated IGF‐2:IGF‐1 ratio." (PMID 38411039, 2024). "For example, in multiple myeloma (MM) cells, IL-6, IGF-1, SDF-1α, tumor necrosis factor-α (TNF-α), and VEGF can promote tumor cell proliferation through the MEK/p42/p44/MAPK signaling cascade." (PMID 38672455, 2024). "have observed that the IGF1/IGF1R axis inhibition enhanced the efficacy of immunogenic chemotherapy, which correlated with an increase in tumor infiltrating effector T cells and a decrease in T-regs, in breast tumor mouse models." (PMID 38420122, 2024). "Irradiated CAFs release IGF1, which mediates IGF1R/IR phosphorylation and activation of downstream signaling in tumor cells." (PMID 38892104, 2024). "We found that exposure to FGF2, FGF18, HBEGF, IGF1, PDGF-BB, and TGFα significantly (p < 0.0001) increased MCL1 expression in tumor cells (by at least 1.2-fold and up to 2-fold) and treatment with the MEKi reduced this response." (PMID 37676378, 2024). "The results showed that IGF-1 mRNA levels were overexpressed in all OC cell lines (OVCAR3, OVCAR8, and OVCAR8 PTX R P) under study compared to the non-tumor ovarian cell line, HOSE6.3." (PMID 39596005, 2024).
tumor (continued). "Upregulation of IL-4/IL-4R signaling in TAMs results in their increased secretion of insulin-like growth factor (IGF-1), which, upon binding to IGF-1 receptor (IGF-1R) on tumor cells, upregulates the PI3K pathway, promoting tumor growth and malignancy." (PMID 38254796, 2024). "Furthermore, IGF-1R’s involvement in modulating the tumor microenvironment, including interactions with immune cells, suggests that combining IGF-1 inhibitors with immunotherapies could bolster anti-tumor immune responses, offering a multi-pronged approach to combat BC." (PMID 39273251, 2024). "Blood glucose and serum insulin, IGF-1 and IGFBP3 were measured at study end when tumor volumes reached 800 mm3." (PMID 38082056, 2024). "The same authors highlighted encouraging effects of pasireotide on PFS and disease control, as well as on reduction of tumor markers (CgA, NSE, IGF-1)." (PMID 37581846, 2024). "Chemotherapy triggers tumor endothelial cells to suppress IGFBP7, and the upregulation of IGF1 activates the FGF4-FGFR1-ETS2 pathway and accelerates the conversion of tumor cells to chemo-resistant tumor stem-like cells." (PMID 38576482, 2024). "The study assessed the effect of E4 co-treatment with LHRH agonist ADT on tumor stimulators, including FSH and IGF-1." (PMID 39408055, 2024). "CAFs secrete high levels of the ligands IGF1 and IGF2, thereby promoting the tumor growth, migration, and invasion as well as drug resistance of IGF1R-expressing tumor cells." (PMID 38892104, 2024). "The IGF-1R is activated in at least 50% of BCs, with its natural ligands, IGF-1 and IGF-2, contributing to tumor growth and survival." (PMID 39273251, 2024). "IGF-1 and CCL20 promote tumour progression, while SIRPα interacts with CD47 expressed on tumour cells to inhibit microglial phagocytosis." (PMID 39364322, 2024). "IGF‐1 is closely related to cell proliferation, differentiation and apoptosis, and also plays an important role in the EMT process of tumour cells as well." (PMID 38842135, 2024). "The presence of miRNA-29b reduces the growth and invasion of tumour cells, with possible interaction with interferon-γ (IFN-γ), IRF1, and IGF1." (PMID 39001340, 2024). "It has been shown that in certain tumor development or physiological processes, TGF-β1 and the IGF1 signaling pathways exhibit reciprocal regulation." (PMID 38972889, 2024). "Insulin-like growth factor IGF1 and insulin-like growth factor binding protein IGFBP6 exert contrasting effects on tumor cells, with pro-tumor and anti-tumor effects, respectively." (PMID 38818409, 2024). "In fact, a decreased production of fibronectin, IGF1 and IGFBP2 by haploinsufficient IGF1R fibroblasts, together with a downregulation of integrins expression in tumour cells, impaired the survival of tumour cells." (PMID 37033265, 2023). "Cancerous thyroid cells can produce IGF-1 and IGF-2 locally: stromal cells secrete IGF-1, while IGF-2 is produced by tumor cells." (PMID 36811728, 2023). "Deletion of the IL30 gene in PC cells inhibits endothelial expression of IGF1, EDN1, ANG and CXCL10 and substantially impairs tumor angiogenesis." (PMID 38087324, 2023). "Six key genes were located within malignant tumor cells and enriched predominantly in the cytoplasm of tumor cells, including PERP, BAK1, VDAC1, FOXO3, AKT3, and IGF1." (PMID 36900213, 2023). "IGF1 has also been elucidated as a dictator CD4+ T cell by enhancing ERβ transcriptional activity and an immuno editor that eradicates new emerging tumor cells in the immune system." (PMID 36900213, 2023). "The two primary IGF-1 pathways are the PI3K/Akt pathway and the MAPK pathway, both of which are essential for promoting the proliferation of tumour cells." (PMID 36890832, 2023). "Moreover, both androgens and estrogens are hypothesized to prevent tumor growth in part by preventing insulin and insulin-like growth factor (IGF) from binding to their receptors and there is evidence of an association between IGF-1 and the risk of CRC." (PMID 37341814, 2023).
tumor (continued). "When co-cultured with MCF-7 BC cell lines, mouse 3T3-L1 adipocytes and human mammary adipocytes increased the release of IGF-1, which increased the expression of FASN in tumor cells and promoted the growth and metastasis of BC." (PMID 36765683, 2023). "Adipocytes increased the secretion of IGF-1 when co-cultured with BC cells, which increased the expression of fatty acid synthase (FASN) in tumor cells and promoted the growth and metastasis of BC." (PMID 36765683, 2023). "MSCs have also been shown to promote tumor angiogenesis through release of VEGF, bFGF, FGF-2, IL-8, IL-6, TNF, IGF-1 and TGF β as well as subsequent transformation into smooth muscle cells and pericytes, coupled with formation of new tumor vessels." (PMID 36926687, 2023). "In response to IL4, TAMs acquire the ability to upregulate expression of insulin-like growth factor 1 (IGF-1), which triggers the signaling of IGF-1R and PI3K, rendering the tumor resistant to CSF-1R inhibition." (PMID 37275361, 2023). "IGF1 promotes tumor growth by activating local prostate MAPK and PI3K signal transduction, revealing the possible existence of the intestinal microbiome-IGF1- prostate axis." (PMID 37265797, 2023). "IGF studies have indicated oncogene transformation, tumor proliferation, and tumor growth regulation by type 1 IGF receptor (IGF-1R), IGF-1, and insulin, identifying IGF signaling a viable therapeutic target." (PMID 37373357, 2023). "Macrophages are known to promote tumor cell migration through the secretion of proteins, such as EGF, CHI3L1, IGF1, FN1, TNC and TGFBI." (PMID 36551640, 2022). "The IL-6 target genes MET, IGF1, MMP3, CEACAM1, MMP1 and WNT5A were upregulated, which enabled the tumour cells to become invasive." (PMID 35022523, 2022). "Insulin-like growth factor 1 (IGF1), VEGF, PDGF, FGF, and CXCL12 can promote tumor angiogenesis, proliferation, migration, and immunosuppression through paracrine production." (PMID 35965504, 2022). "The IGF-1/IGF-1R complex increases the expression of VEGF, which promotes angiogenesis and tumor development." (PMID 35203638, 2022). "The morphology and size of transplanted tumor were observed, which presented that the volume and weight of transplanted tumor increased in nude mice injected with CAOV4 cells harboring OE-WISP1, while contrary results were seen upon IGF1 antibody." (PMID 35964060, 2022). "KD can affect tumor cell growth by lowering insulin and IGF-1 levels, thereby reducing receptor tyrosine kinase-dependent signaling pathways such as PI3K-Akt-mTOR for tumor cell proliferation and tumor growth." (PMID 36432618, 2022). "In ILC, both PAPPA and IGF1 were significantly upregulated in the stroma compared to the epithelium (p < 0.0001), while IGF1R was found predominantly in the tumor epithelium (p < 0.05)." (PMID 35205651, 2022). "Similar to IGF-1, insulin levels were significantly increased in HFD mice compared to both NCD and CR at tumour endpoint." (PMID 35908046, 2022). "The combination of IGF1 in TME and its receptor in TCs, IGF1R, activated the downstream PI3K signaling pathways to support tumor regrowth and led to drug resistance." (PMID 35800363, 2022). "Among these 9 candidate targets, AGT, DRD2, IL-1B, and IL-6 were significantly increased in primary tumor compared with the normal tissues, while ALB, IL-10, and IGF1 were significantly decreased in COAD tissues." (PMID 35280511, 2022). "In vivo, IGF-1 expression was reportedly reduced in xenografts of Los Angeles PCa-4 (LAPC-4) in mice fed a low-fat diet, and tumor volume was suppressed." (PMID 35370981, 2022). "In univariate regression analyses, the peak GH response to GHRP-2 significantly and negatively correlated with BMI, serum creatinine level, and tumor diameter, and it was positively correlated with estimated GFR, IGF-1 SD score, and free thyroxine levels." (PMID 35452483, 2022).
tumor (continued). "In a contrasting mechanism, lncRNA lncCCLM is a potential tumor suppressor in cervical cancer, interacting in the cytoplasm with the RNA-binding protein STAU1 to promote its binding and degradation of IGF-1 mRNA." (PMID 35597813, 2022). "A moderate statistically significant positive correlation occurred between tumor size and CRF and CH, and a moderate positive correlation was observed between IGF-1 and CH prior to surgery." (PMID 36431227, 2022). "Deletion of IL30 dramatically downregulated BCL2, NFKB1, STAT3, IGF1 and CXCL5, whereas tumor suppressors, primarily SOCS3, were upregulated." (PMID 36224639, 2022). "Malignant ascites contains various metastasis-promoting mediators, produced by both tumor cells and CAFs, such as TGF-β1, HGF, GRO-1 and IGF-1." (PMID 35682890, 2022). "Other possible mechanisms supporting tumor cell development are changes in systemic levels of growth hormones, such as somatotropic hormone (STH) and insulin-like growth factor 1 (IGF1)." (PMID 35574343, 2022). "IGF-1 and IGF-1R are overexpressed in the majority of Ewing sarcoma cell lines and have been previously studied as potential therapeutic targets in tumor treatment." (PMID 35454895, 2022). "IGF-1 is overexpressed in SFT, and treatment regimens using figitumumab, a fully human IgG2 anti-IGF-1 (IGF-1R) monoclonal antibody, demonstrated tumor responses in a few patients with advanced SFTs." (PMID 35205812, 2022). "Currently, there are many tumor treatments based on IGF, such as blocking the synthesis and secretion of IGF-1, blocking the binding of IGF-1 to its receptor, downregulating IGF-1, downregulating and antagonizing IGF-1R, and blocking receptor activity." (PMID 35372035, 2022). "As regulated by the primary tumor, MDSCs arrived in the metastatic organs before the tumor cells and conditioned it to promote tumor seeding by secreting b-FGF, IGF-1, IL-10, IL-4, IL-1β, SDF-1, and MCP-1." (PMID 35267547, 2022). "Activating the cells with IGF1 enhanced the expression of the integrins α2, αV, β1, activated FAK, and increased tumor cell adhesion and chemotaxis." (PMID 35626034, 2022). "Particularly, in addition to the tumor immune escape pathway, genetic markers belonging to the cytokines/interleukins, including CXCL8, CCL5, CCR5 and angiogenic mediators including IGF1, IRF3, NOS2, appear to be the most promising." (PMID 36432658, 2022). "The role of hsa-miR-508-5p upstream of IGF1, CHEK1 and CCNB1 in IDD remains to be explored, but it has been extensively studied in various tumour tissues and cardiovascular." (PMID 36175893, 2022). "Protein restriction reduced insulin-like growth factor 1 (IGF-1) in blood and thus inhibited the IGF-1/IGFR1/PI3K/AKT/mTORC1 axis in tumor cells, TAMs, and Tregs, activating anti-tumor T cells." (PMID 35062950, 2022). "Reduced levels of IGF-1 lead to development of GH resistance, decreased expression of GHR due to hepatocellular damage by tumor cells, as well as, existence of feedback circuit at endocrine and paracrine loops." (PMID 36374927, 2022). "Diets that lower glucose and elevate D-β-OHB can also reduce circulating levels of insulin-like growth factor 1 (IGF-1), a known driver of tumor growth." (PMID 36059707, 2022). "The knockdown of the SNCG gene leads to the inhibition of IGF-1 and IGF-1R, and, consequently, cell proliferation and tumor growth." (PMID 35203638, 2022). "IGF1 was also expressed in the CAFs while IGFR1 was predominantly expressed in the tumor cells: STC1, STC2 and IGFBP4 were expressed in both tumor cells and CAFs." (PMID 35205651, 2022). "The results demonstrate that the expression of EGFR, IGF1, PTGS2, FGF1, CAV1, and PLCB1 were significantly different (p < 0.01) in PABC tissues as compared to non-tumor tissues, with a similar pattern to that observed in the microarray analysis." (PMID 36035177, 2022).